IL1B (interleukin 1 beta)
Diseases named in the same sentence as IL1B in open-access papers (continued):
Sharing a sentence is not in itself a finding about the gene and the disease.
glioma (continued). "Levels of IL-1β and TNF-α were significantly increased in sensitive individuals, indicating the immunosuppression induced by glioma was reversed in sensitive mice." (PMID 36927689, 2023). "Blockade of IL-1β generation or inhibition of PKCδ, GPD2 pT10 provides us with potential treatment strategies for glioma." (PMID 37012233, 2023). "Tumor necrosis factor-alpha (TNF-α) and Interleukin-1 beta (IL-1β) can induce the production of the small heat shock protein, CRYAB (HspB5) in U373 glioma cells, and U373-secreted exosomes." (PMID 37373314, 2023). "Upregulated LINC01116 can increase neutrophil recruitment by stimulating the production and secretion of IL-1β via recruiting DDX5 to the IL-1β promoter and ultimately facilitating glioma proliferation." (PMID 37637063, 2023). "A significant TNFα inhibition by both KPFs on the glioma cell lines evaluated was observed, and only KPF-BBR was able to significantly inhibit IL-1β on the NG-97 cells." (PMID 37445894, 2023). "DAMPs induces microglia in the area surrounding tumor necrosis to express IL-1β in a TLR-mediated manner, which induces glioma cells to release a range of cytokines such as CXCL8,CCL2, IL-1β and IL-6." (PMID 37700840, 2023). "Three Gene Expression Omnibus datasets were analyzed and revealed that IL‐1β levels were positively correlated with PD‐L1 and CCL2 expression in ovarian cancer, NSCLC, and glioma." (PMID 37009412, 2023). "Of course, the M1-type of TAMs secrete interleukin-1β (IL-1β) and tumor necrosis factor (TNF-α) to promote T cell activation to kill glioma cells, but this effect is minimal in the glioma microenvironment." (PMID 37375698, 2023). "CD44 knock-out in myeloid cells affected their ability to upregulate TNF-α and IL-1b, and most notably, to increase MMP9 production in response to gliomas." (PMID 35992852, 2022). "The IL-1β, IL-18, TNF-α, and other cytokines in microglia are released and act on glioma to promote tumor cell proliferation." (PMID 36713560, 2022). "Caspase-8 can also stimulate the NF-kB pathway and upregulate the secretion of IL-8, IL-1β, IL-6, VEGF and MCP-1, improving temozolomide resistance in gliomas." (PMID 36605437, 2022). "M2 TAMs produce IL-1β, which in turn leads to phosphorylation of the glycolytic enzyme GA3PDH in glioma cells through PIK3-mediated activation of protein kinase (PK)Cδ." (PMID 34073734, 2021). "Wogonin also inhibits the progression of gliomas by downregulating the secretion of the inflammatory cytokines TNF-α, IL-6, and IL-1β." (PMID 33897434, 2021). "The data shown in our study indicate that overexpressed JMJD1C increases the expression of M1 markers (IL‐1β, TNF, CXCL9, IL‐23, ROS1, IL‐12a, and IL‐12b) both in the glioma mouse models and in the CD14+ monocytes co‐cultured with glioma cells." (PMID 34586733, 2021). "IL-1β and TGF-β triggered neurosphere formation and upregulation of tumor stemness genes (Bmi-1 and nestin) in glioma LN-229 cells." (PMID 34439380, 2021). "Furthermore, cyclooxygenase-2 (COX-2), cytosolic phospholipase, interleukin-1β (IL-1β), and the β-amyloid precursor protein of proinflammatory and neurodegenerative gene were found to be upregulated in the American Tissue Culture Collection of glioma and glioblastoma." (PMID 34066808, 2021). "TAMs have been shown to release a plethora of factors that stimulate tumor growth and invasion, including TGF-β, IL-1β, IL-6, stress-inducible protein 1 (STI1), and epidermal growth factor (EGF) by acting on GSCs in the perivascular niche and glioma cells." (PMID 33766119, 2021). "The upregulation of NLRP3 affects human glioma progression by activating the AKT signaling pathway and IL-1β/NF-kappaB p65 signaling, thus promoting migration and invasion." (PMID 34064909, 2021). "Bioactive triterpenoid ursolic acid (UA) isolated from Rosmarinus officinalis was found to suppress IL-1β/ TNF-α and downregulate MMP-9 protein in rat glioma cells, thereby preventing cancer cell proliferation." (PMID 34439380, 2021).
glioma (continued). "In glioma cells, CD133, a cancer stem cell marker, raises the expression of IL-1β and its downstream chemokines, including CCL3, CXCL3, and CXCL5." (PMID 33429364, 2021). "The expression of COX-2 in glioma cells promoted the anabolic metabolism of PGE2, up-regulating the expression of IL-1β and CXCL1 to recruit neutrophils." (PMID 34211978, 2021). "In this study, we found that the expression of IL-1β steadily decreased after knockdown of LINC01116, thereby reducing neutrophil recruitment and glioma proliferation." (PMID 32358484, 2020). "CSF2 depletion from both LN18 and U87 glioma cells blocked up-regulation of the anti-inflammatory IL10 expression and led to induction of IRF7 and IL1β mRNA levels in stimulated microglia." (PMID 32390004, 2020). "We show that CEBPD is responsive to IL-1β stimulation and enhances the transcription and expression of PDGFA, which, in turn, promotes glioma stemness." (PMID 31300060, 2019). "Co-culture of BMSCs and glioma cells was found to inhibit angiogenesis in gliomas by down-regulating the expression of angiogenic markers such as PDGF-BB, IGF-1, FGF-2, and IL-1b." (PMID 31864321, 2019). "Our results along with previous studies suggest that IL-1β, after being secreted by activated microglia, induces its own production by stimulating NLRP3 inflammasome complex in glioma cells, monocytes, and other cell types." (PMID 29885667, 2018). "Since previous results showed that higher IL-1b and CCR1 levels were found in GBM array data of TCGA, we also measured endogenous protein levels of IL-1b and CCR1 in astrocyte and glioma cell lines." (PMID 28389653, 2017). "To test the effects of IGF-1 on endogenous levels of IL-1b and CCR1 in glioma cells, we measured mRNA and protein levels of IL-1b and CCR1 in IGF-1-stimulated glioma cells by real-time qPCR assays and immunoblotting analyses." (PMID 28389653, 2017). "In our present study, activation of the TLR4 signaling pathway promoted the production of IL-1β, IL-6, IL-10, MCP-1, MIP-1α, and TNF-α in glioma CD133+ CSCs." (PMID 28881826, 2017). "LPS induced ROS in U-87 human glioma cells which allevated pro-inflammatory cytokines (TNF-α, IL-6 and IL-1β)." (PMID 27435304, 2016). "Our group showed that conditioned medium from glioma cells increased STAT3 activity in microglia cells, resulting in overexpression of IL-6 and IL-10 and downregulation of IL-1β." (PMID 23864876, 2013). "In summary, we have used a human LN-229 glioma cell line to examine the effect of IL-1β/TGF-β signaling on induction of self-renewal and oncogenic capability of glioma cells." (PMID 22330721, 2012). "Here, we demonstrate that the combination of IL-1β and TGF-β can promote self-renewal and oncogenic capability of glioma cells by inducing expression of stemness factor genes Bmi-1, LIF and Notch-2." (PMID 22330721, 2012). "We previously reported that IL-1β significantly induces the activation of p38 MAP kinase, SAPK/JNK and Erk 1/2 in C6 glioma cells." (PMID 21682888, 2011). "We previously reported that IL-1β induces activation of IκB, p38 MAP kinase, SAPK/JNK, Erk 1/2 and STAT3 in C6 glioma cells." (PMID 21682888, 2011). "In the present study, our results suggest that IL-1β induces IL-6 release through the IκB-NFκB pathway, p38 MAP kinase, SAPK/JNK and JAK-STAT3 pathway in C6 glioma cells." (PMID 21682888, 2011). "In vitro research using murine BV2 microglial cells demonstrated that conditioned media from glioma cells might activate microglial cells by increasing the mRNA levels of cyclooxygenase-2 (COX-2), tumor TNF-α, IL-6, iNOS, and IL-1β." (PMID 40727443, 2025). "A comparison of concentrations within the same glioma grades in plasma samples and homogenates showed statistically significant differences in the case of HIF-1α in grades G2 and G4, for ANG-2 in grade G1, and for IL-1β in grades G2 and G4." (PMID 40429943, 2025).
glioma (continued). "SP increased the expression and secretion of interleukin-8 (IL-8), a target gene controlled by NF-κB, and this effect is specific, since an NK-1R antagonist completely prevented NF-κB activation in response to SP, but not to IL-1β, in U-373 MG glioma cells." (PMID 39941886, 2025). "Furthermore, we found that calycosin inhibited proliferation, migration, and invasion in U87 and U251 glioma cells, and decreased CXCL10 expression in a dose-dependent manner, along with its downstream effectors such as NLRP3, NF-κB, and IL-1β." (PMID 38461458, 2024). "Similarly, Ho and coworkers observed a reduced proliferation of glioma cells in GASC/glioma co‐cultures and a lower expression of PDGF‐BB and IL‐1β compared with controls." (PMID 36300592, 2023). "Additionally, a study by Sarkar and Yong showed that increases in IL-1β and TNF-α levels were positively correlated with glioma cell invasiveness and a corresponding elevation of MMP-2 and MMP-9 proteins." (PMID 36675073, 2023). "Tim-3/Gal-9 did not trigger IL-1β secretion but were strongly positively correlated with caspase-1 activity as they induced programmed cell death in glioma cells." (PMID 35216164, 2022). "Although inflammasome-mediated pyroptosis in glioma has not been reported, IL1β has been shown to be a serum marker in glioblastoma, which prompted us to explore potential pyroptosis pathways in glioma." (PMID 36199426, 2022). "IL-1β has been intensively studied, and IL-1β production by M2 macrophages promotes glycerol-3 -phosphate dehydrogenase (GPD2) phosphorylation, which, in turn, accelerates the glycolytic rate to promote glioma cell proliferation." (PMID 36588722, 2022). "Also, a study revealed that IL-1β secreted by both microglia and macrophages stimulated the p38 mitogen-activated protein kinase (MAPK) pathway in glioma cells, which in turn results in augmented secretion of CCL2—the agonist for CCR2 on microglia." (PMID 35419058, 2022). "Therefore, further studies are needed to explore the preliminary link between NLRC4-mediated IL-1β secretion and tumor progression, potentially positioning the NLRC4-IL-1β pathway as a potential therapeutic target for inhibition of glioma and other cancers." (PMID 34276697, 2021). "Following a 24 hours incubation of hEGFRvIII:CD3 bi-scFv, PBMCs, and human glioma cells U87-MG-EGFRvIII or control U87-MG cells, we harvested the supernatant and measured the concentration of IFN-ɣ, IL-6, IL-1β, MIP-1α, GM-CSF, and TNFα using the Luminex multiplex platform." (PMID 32273346, 2020). "However, when human monocytes were exposed to IL1β/IFN-γ, cytokines that are elevated in glioma subjects, or to the toll-like receptor-4 ligand LPS, demeclocycline elicited a further increase in TNF-α levels in activated cells." (PMID 32153581, 2020). "Moreover, intragastric administration of PHOR in a dose of 1.5 g/kg BW to a nude mouse model of glioma remarkably slowed glioma growth and increased the levels of TNF-α, IL-1β, and IL-6 through the activation of PI3K/AKT signaling." (PMID 31281578, 2019). "Additionally, we demonstrate that IL-1β can induce CEBPD transcription and expression in glioma cells, which, in turn, promotes glioma stemness." (PMID 31300060, 2019). "Studies also show that IL-1β can activate STAT3 in osteoblasts, Th17, and glioma." (PMID 31300060, 2019). "IL-1β and its receptor are highly expressed in the neurons and glia of patients with TLE caused by focal cortical dysplasia and neuroglial tumors, where expression in brain tissue without these alterations is negligible." (PMID 29401729, 2018). "Similarly, levels of IL-1β and HSP60 get significantly elevated in glioma tissue in comparison to control." (PMID 29885667, 2018). "IL-1b and CCR1 protein levels were higher in glioma cells than that in astrocyte cells." (PMID 28389653, 2017). "Similarly, the produced HIF-1 silencing diminished HLA-G protein expression in glioma cells (A17, U87MG) after IL-1β induction of HIF-1, even if in normoxia." (PMID 28781970, 2017).
glioma (continued). "Furthermore, combined IL-1b and TGF-β treatment induced neurosphere formation and increased tumorigenicity of glioma cells." (PMID 28389653, 2017). "Consequently, IGF-1-enhanced cytokine IL-1b and CCR1 signaling via inhibiting miR-181d is involved in glioma progression." (PMID 28389653, 2017). "For human glioma, inhibition of IRE1α resulted in down-regulating of VEGF-A, IL-1β, IL-6, and IL-8." (PMID 26633383, 2015). "In gliomas, it has been shown that IL1β in combination with TGFβ increases the neurosphere-forming ability and tumorigenicity of the LN-229 glioma cell line, although the mechanism was not elucidated." (PMID 25987130, 2015). "As shown, the IL-6 inhibitor SC144 blocked the action of LPS-induced hBMVEC on C6 glioma cell sCp gene expression, while the IL-1β inhibitor IRAP had no notable effect." (PMID 25311416, 2014). "Our studies of human and mouse astrocytes and glioma cells demonstrate that IL-1α mRNA and protein are co-induced and co-regulated with IL-1β, as in myeloid cells (data not shown)." (PMID 25054228, 2014). "C6 glioma cells were incubated for 6 h in the absence of either cytokine (control) and in the presence of IL-1β, IL-6, or both." (PMID 25311416, 2014). "Therefore, based on these findings, it is probable that IL-1β induces IL-6 release through activation of the IκB-NFκB pathway, p38 MAP kinase, SAPK/JNK and JAK-STAT3 pathway in C6 glioma cells." (PMID 21682888, 2011). "Other studies have reported an increase in cell content of S100B in C6 glioma cells after 24 h of exposure to IL-1β or no change in astrocyte cultures after 48 h and a decrease in S100B content in cultured astrocytes after 3 days of exposure to TNFα." (PMID 21970823, 2011). "Notably, there was overexpression of various cytokines, including IL-1β, IL-4, IL-6, IL-8, IL-10, TGF-β and TNF in the patient cohort, which was unsurprising given that these cytokines serve primarily immunosuppressive roles in the glioma microenvironment." (PMID 41034696, 2025). "Monocytes express a wide range of PRPs including TLRs, NLRs, RLRs and CLRs which in glioma TME enable immunosuppression (through IL-10 and TGF-β cytokine release), fuel inflammation (through the secretion of IL-1β and IL-18) and preserve tumor growth (through VEGF, MMPs, and IL-1β expression)." (PMID 41157253, 2025). "Furthermore, IL-1β, produced by M2 macrophages, activates the phosphorylation of glycerol-3-phosphate dehydrogenase (GPD2) on threonine 10 (GPD2 pT10) in glioma cells, which enhances the affinity of GPD2 pT10 to substrate, and improves the catalytic rate of glycolysis in glioma cells." (PMID 38632627, 2024). "Indeed, a prior study including the mouse glioma cell line GL261 demonstrated that anti–IL-1β treatment increased the survival of female, but not male, mice bearing these tumors." (PMID 37966120, 2023). "IL-1β is a well-known cytokine that upregulates mRNA expression of pro-inflammatory cyclooxygenase 2 (COX-2), which, together with prostaglandin PGE2, interacts with PGE2 receptors, and thereby enhances glioma aggressiveness by maintaining glioma cell stemness and the inflammatory microenvironment." (PMID 38003396, 2023). "Interestingly, not only can IL-1β promote hypoxia-induced apoptosis in GBM through the inhibition of the HIF-1/AM axis, but it also induces tumorigenicity and promotes the formation of glioma spheres in LN-229 glioma cells." (PMID 35784465, 2022). "Inflammasome/GSDMD/IL-1β axis has not been investigated in glioma." (PMID 34830775, 2021). "Meanwhile, we confirmed that the level of DDX5 enrichment in the IL-1β promoter region of glioma cells was significantly decreased after knockdown of LINC01116, indicating that LINC01116 could recruit DDX5 to the IL-1β promoter region to activate transcription." (PMID 32358484, 2020).
glioma (continued). "A discussion of the pathophysiological role of cytokines in glioma is reviewed elsewhere, and the role of several of the specific genes demonstrating enrichment of the cytokine-cytokine receptor interaction KEGG pathway has previously been discussed (CD70, IL-12β, IL-1β)." (PMID 31475119, 2019). "Thus, we analyzed the expression of a panel of common M1 (IL-1b, IL-12, iNOS, TNFα) and M2 (TGFβ, IL-10, ARG1) phenotype markers and the immune suppressive PD-L1 (CD274) in control and Pdpn-deleted BMDM co-cultivated with four different glioma cell lines." (PMID 30972297, 2019). "Coadministration of human BM‐MSCs and glioma cells also significantly reduced tumor size and vascular density, with MSCs downregulating the expression of angiogenic molecules 18 in glioma cells and BM‐MSC glioma cocultures showing reduced expression of PDGF‐B and IL‐1β." (PMID 28170195, 2017). "Furthermore, by treating with IL1b recombinant proteins, or respectively transfecting with CCR1 and miR-181d genes, we found that both IL-1b and CCR1 could obviously induce glioma cell invasion." (PMID 28389653, 2017). "Our finding indicates that glioma cells without self-renewal capability in standard conditions could also contribute to glioma malignancy when cytokines, such as IL-1β and TGF-β, are present in the tumor environment." (PMID 22330721, 2012). "The effect of IL-1β on α-synuclein in cultures of primary neurons is generally consistent with prior reports that the cytokine induces α-synuclein protein in macrophages and a glioma cell line but not in primary astrocytes." (PMID 16542445, 2006). "In addition, M2 macrophages produce IL-1β, which plays a vital role in the phosphorylation of the glycolytic enzyme glycerol-3-phosphate dehydrogenase (GPD2) at threonine 10 (GPD2 pT10) through phosphatidylinositol-3-kinase-mediated activation of protein kinase-delta (PKCδ) in glioma cells." (PMID 37012233, 2023). "Hyperbaric oxygen therapy (HBOT) could inhibit glioma cell proliferation and inflammatory cell infiltration, and exert a sensitizing effect on ACNU therapy partially through enhancing oxygen pressure (PO2) in tumor tissues and lower expression levels of HIF‐1α, TNF‐α, IL‐1β, VEGF, MMP9, and NF‐κB." (PMID 27734611, 2016). "Despite recent advances in neuro-oncology, the contribution of IL-1β and TGF-β to glioma development and recurrence has not been clearly delineated." (PMID 22330721, 2012).